TMPRSS2 (transmembrane serine protease 2)
Diseases named in the same sentence as TMPRSS2 in open-access papers (continued):
Sharing a sentence is not in itself a finding about the gene and the disease.
infection (continued). "Infection of Vero-TMPRSS2 (Vero E6 cells stably expressing the transmembrane serine protease TMPRSS2), Caco-2, and Huh-7.5 cells was monitored by staining of the cells with antibodies against the SARS-CoV-2 nucleocapsid (N) protein." (PMID 36804936, 2023). "In all these studies, the arginine residues play a catalytic role in basic cleavage sites (R685-S686 and R815-S816) for the S-protein’s cleavage and triggering infection induced by furin and TMPRSS2 proteases." (PMID 36851526, 2023). "Since TMPRSS2 downregulation has been shown to reduce virus titers and infectivity in vitro and in vivo, TMPRSS2 is thought to be a good target for the treatment of infections with viruses that enter the host using this protease." (PMID 36830955, 2023). "SARS-CoV-2 uses this enzyme to facilitate the entry to target cells and to initiate infection mediated by transmembrane serine protease 2 (TMPRSS2) and cathepsin L." (PMID 37189823, 2023). "Altogether, we have shown that Omicron Spike residue F375 reduces infection, Y655 decreases TMPRSS2 responsiveness, and K856 decreases cell–cell fusion rate." (PMID 37243215, 2023). "Another study showed that in the airways of TMPRSS2‐knockout mice, Omicron infection efficiency is significantly reduced." (PMID 37193304, 2023). "Next, we sought to determine MoDC-mediated trans-infection of Vero-E6 TMPRSS2 cells by B8-dIgA-bound pseudovirus." (PMID 37542391, 2023). "ACE2 and TMPRSS2 are involved in early stages of infection, while MX1 implication takes place in later stages." (PMID 37287057, 2023). "In this study, ASOs targeted against the SARS-CoV-2 genome and host entry factors, ACE2 and TMPRSS2, were designed and tested for their ability to inhibit cellular infection by SARS-CoV-2." (PMID 36735698, 2023). "BA.5 would thus appear to have an increased capacity for infection of brain organoids via a TMPRSS2-independent mechanism." (PMID 38075874, 2023). "Reducing or inhibiting TMPRSS2 was proposed to reduce the infection rate and case severity by altering virus entry." (PMID 36754974, 2023). "The organoid 2525UL expresses low TMPRSS2, providing an explanation for the low infection rate in 2525UL." (PMID 36827975, 2023). "Based on these results we not only verified angiotensin I converting enzyme 2 as well as the serine protease TMPRSS2 on the protein level, but in addition also demonstrated productive infection of “Arlo” with SARS‐CoV‐2." (PMID 36748276, 2023). "Although no firm opinion exists on the primary physiological function of TMPRSS2, it has gained a great deal of attention for a non-physiological role in priming viral glycoproteins as a precursor to host infection." (PMID 37987478, 2023). "TMPRSS2 mRNA expression was even lower in the organoids than in K18-hACE2 brains, with infection of human neurons shown to be TMPRSS2-independent." (PMID 38075874, 2023). "In conclusion, our study indicates that TMPRSS2, although only slightly expressed in dendritic cells, alters the immune response during infection simulation." (PMID 36830955, 2023). "With cleavage by transmembrane protease, serine 2 (TMPRSS2), on the cell surface, the fusion pore is formed to provide an infection channel for the viral genome entry into the cell." (PMID 37063897, 2023). "In this commonly used cell model, susceptibility to viral entry was also strictly dependent on ACE2; however, co-expression of TMPRSS2 greatly increased cellular infection." (PMID 36979408, 2023). "We cultured autologous virus in Vero E6/TMPRSS2 cells from Infection Day 297, when we first detected twenty-five new consensus mutations including Spike E484T, and performed a neutralization assay with four commercially available antibodies." (PMID 37692895, 2023). "TMPRSS2 is critical for infection, as it modifies SARS-CoV-2 spike protein after binding to ACE2 and facilitates virus and host membrane fusion." (PMID 37037851, 2023).
infection (continued). "To further confirm that this phenomenon is also reflected in their ability to suppress infection, we used TMPRSS2 overexpression cells and found that the inhibitory activity of Dauricine and Isoliensinine declined in the TMPRSS2-expressing cells." (PMID 38001915, 2023). "This explains our findings of attenuated infection kinetics as well as less severe CPE formation of TMPRSS2-expressing lung epithelial Calu-3 cells infected with Omicron BA.1 and BA.2 variants." (PMID 37001587, 2023). "NR4A2 knockdown or interferon‐λ2/λ3 stimulation downregulates the expression of NR4A2, ACE2, and TMPRSS2, thereby inhibiting the infection." (PMID 37428471, 2023). "Excessive amounts of ACE2 and TMPRSS2 are also seen in the human reproductive system, indicating a possible infection in the primordial germ cells." (PMID 36124445, 2023). "Pitstop2 alone lowered infection when compared to the DMSO control, while the addition of TMPRSS2 inhibitors increased infection above that observed with Pitstop2." (PMID 38033586, 2023). "For example, miR-147-3p in the gut targets the TMPRSS2 enhancer and increases intestinal inflammation following infection with SARS-CoV-2." (PMID 37559103, 2023). "As in the case of hESC, more differentiated cells derived from iPSCs can become susceptible to the infection, especially if the daughter cells express high levels of ACE2 and TMPRSS2." (PMID 36453030, 2023). "We confirmed that coexpression of ACE2 and TMPRSS2 markedly increased wild-type SARS-CoV-2pp infection, and this was significantly decreased by amuvatinib." (PMID 36995225, 2023). "While the catalytic domain of TMPRSS2 is well documented for its pivotal role in mediating the SARS-CoV-2 membrane route of infection, the significance of other regions within TMPRSS2 has received limited attention." (PMID 37896901, 2023). "The presence of the angiotensin-converting enzyme-2 (ACE2) receptor, as well as transmembrane serine protease 2 (TMPRSS2), are essential as they promote viral activation in the host cell and, thus, infection." (PMID 36673058, 2023). "At 24 h post-infection, total RNA was isolated and the mRNA expression of TMPRSS2 and the related protease TMPRSS4 was determined by RT–qPCR." (PMID 37208193, 2023). "Infection with SARS-CoV-2 was inhibited in Vero-Transmembrane Serine Protease 2 (TMPRSS2) and Calu-3 cells by S-217622 in a dose-dependent manner." (PMID 36327352, 2023). "Omicron can infect cells in a TMPRSS2-independent manner, maximizing the receptor-mediated endocytosis route of infection." (PMID 37243215, 2023). "In contrast to early omicron variants, original ancestral isolates show a preference for TMPRSS2 utilization, and rapid fulminant infection of K18-hACE2 brains by such viruses is well described." (PMID 38075874, 2023). "This is a promising result because this model accurately recapitulates the initial site of infection of this virus, using the TMPRSS2-dependent (membrane fusion) pathway." (PMID 36834705, 2023). "In conclusion, this report provides evidence of the presence of ACE-2, TMPRSS-2, and Neuropilin-1 proteins on primary pericytes and astrocytes and has demonstrated infection of SARS-CoV-2 in these cells." (PMID 37239978, 2023). "Our analysis revealed that TMPRSS2-Spike physical interaction facilitates membrane infection, provided that TMPRSS2 is enzymatically competent." (PMID 37896901, 2023). "A very strong argument in favor of this interpretation is given by the in vitro infection kinetics comparing the Delta and Omicron in Calu-3 cells, which have high level expressions of TMPRSS2 and in (TMPRSS2)-overexpressing VeroE6 cells." (PMID 36768244, 2023). "TMPRSS2 mRNA expression levels in K18-hACE2 mouse brains are very low, so TMPRSS2-independent infection would likely be selected as the virus spreads within the brains." (PMID 38075874, 2023).
infection (continued). "The growth kinetics of mutants was evaluated at 0, 24, 48, and 72 hpi in Vero E6/TMPRSS2 cells infected at a multiplicity of infection (MOI) of 0.001." (PMID 37623322, 2023). "Omicron exhibits reduced TMPRSS2-dependency, enabling infection of TMPRSS2-positive cells through both entry pathways, facilitated by the presence of Omicron-specific Spike Y655 residue." (PMID 37896901, 2023). "The expression levels of Nr4a2, Ace2, and Tmprss2 proteins, as well as the infection level of Omicron BA.5 pseudovirus, were significantly higher in the lung and testis tissues of BaP‐treated hamsters compared to dimethyl sulfoxide (DMSO)‐control hamsters." (PMID 37428471, 2023). "Inhibitors of TMPRSS2 and of endocytosis, two pathways of viral entry, were tested to identify those that blocked infection." (PMID 38033586, 2023). "Our goal was to examine the effects of JUUL “Virginia Tobacco” and its individual chemicals on ACE2, TMPRSS2, and infection of BEAS-2B cells by the SARS-CoV-2 virus." (PMID 37037851, 2023). "By entering human cells through the angiotensin-converting enzyme 2(ACE2) receptor and Transmembrane Serine Protease 2(TMPRSS2), SARS-CoV-2 can cause infection." (PMID 37347115, 2023). "Third, previous reports have also described the potential furin independent spike priming by cysteine proteases such as cathepsin B/L (CatB/L) for aiding the infection in potential TMPRSS2- cells." (PMID 35138160, 2022). "Since ciliated and club-goblet cells are located at the apical surface, production and secretion of SERPINA1 from these cells in vivo would result in inhibition of TMPRSS2 at the natural site of infection." (PMID 35532162, 2022). "Specific proteases, such as furin, trypsin, cathepsin, or serino-protease (transmembrane serine protease 2-TMPRSS2), are involved in the virus entry into the cell, leading to the intracellular infection signal." (PMID 35664675, 2022). "To further investigate the role of TMPRSS2 in Calu-3 cells, we treated infected Calu-3 and VeroE6 cells with chloroquine and monitored the infection and viability." (PMID 36298757, 2022). "Host proteases such as transmembrane serine protease 2 (TMPRSS2) then cleaves the viral S protein causing a conformational change, allowing permanent fusion of the viral and host cell membranes, and thus infection." (PMID 35721552, 2022). "In our study, we elaborated on the expression patterns of ACE2 and TMPRSS2 to assess the dependency of the virus for infection in a spatial context." (PMID 35255100, 2022). "We next infected Calu-3 lung cells (which are known to express endogenous TMPRSS2) with live isolates, and observed significantly greater viral replication for Delta than Omicron, manifesting as early as 24 h after infection." (PMID 35104837, 2022). "Considering the significantly lower expression of ACE2 in the “upper” region and the necessity of ACE2 and TMPRSS2 expression for infection." (PMID 35255100, 2022). "SARS-CoV-2 infection is visualized in regions where ACE2 and TMPRSS2 expression is present, confirming the necessity of both proteins for infection." (PMID 35255100, 2022). "The SARS-CoV-2 virus uses angiotensin-converting enzyme 2 (ACE2) and transmembrane protease serine 2 (TMPRSS2) to facilitate infection." (PMID 35664675, 2022). "SARS-CoV-2 spike (S) glycoprotein interacts with ACE2 in host cells and depends on the type II transmembrane serine protease (TMPRSS2) for infection." (PMID 35734825, 2022). "TMPRSS2 is expressed in many human tissues and plays a critical role in spreading the infection of viruses including Coronavirus with a central in starting the entire host-pathogen interaction initiated with the physical binding of ACE2 to S-protein." (PMID 36228008, 2022). "Knockout of TMPRSS2 or deletion of FCS sequences also resulted in impaired infection, which was due to low viral titers that were shed from an infected ferrets animal model, resulting in reduced transmission to cohoused sentinel animals." (PMID 35458533, 2022).
infection (continued). "One round of VSV-SARS-CoV-2-Wuh infection was examined in VeroE6 cells overexpressing TMPRSS2 (VeroE6+TMPRSS2)." (PMID 36122200, 2022). "Whole lung lobes of SARS-CoV-2 infected Syrian hamsters and control animals were stained using a variety of antibodies for ACE2, TMPRSS2, and the viral nucleoprotein to detect the functional receptor, cellular protease, and location of infection." (PMID 35255100, 2022). "Among the docked compounds, remdesivir showed excellent binding in the active pocket of SARS-CoV-2 RdRp, and human TMPRSS2, a protein facilitating infection with the virus." (PMID 35886696, 2022). "E64d, a cathepsin L inhibitor, significantly inhibits endosomal SARS-CoV-2 infection mainly in the absence of TMPRSS2 while camostat, a serine-protease-inhibitor, inhibits membrane-fusion-mediated infection in the TMPRSS2 positive cells." (PMID 35388061, 2022). "The human serpin (serine protease inhibitor) alpha-1 antitrypsin (A1AT) shows inhibitory activity for TMPRSS2, and has previously been found to suppress cell infection with SARS-CoV-2." (PMID 36293378, 2022). "Infection by SARS-CoV-2 through ACE2 occurs in synergy with the host’s transmembrane serine protease 2 (TMPRSS2)." (PMID 35892857, 2022). "The inhibition of TMPRSS2 expression by estrogens can prevent the infection since TMPRSS2 and ACE2 are co-expressed, i.e. “interact” at transcriptional level." (PMID 35983046, 2022). "In vitro studies have shown that TMPRSS2 inhibitors prevent primary airway cell and organoid infection by SARS-CoV and SARS-CoV-2." (PMID 35104687, 2022). "Measurements of the sizes of the floating syncytia in the infected VeroE6/TMPRSS2 culture indicated that the syncytia stimulated by B.1.617.2/Delta infection were significantly (3.6-fold) larger than those stimulated by B.1.1 infection." (PMID 34823256, 2022). "The requirement for SARS-CoV-2 spike glycoprotein priming by TMPRSS2 during Caco-2 cell infection has been demonstrated using drug-inactivation of TMPRSS2 that partially blocked viral entry." (PMID 35601094, 2022). "For effective infection, the host transmembrane serine protease-2 (TMPRSS-2) cleaves to the S2 subunit of the protein (Glowacka and others 2011; Matsuyama and others 2020)." (PMID 35674675, 2022). "The receptor-binding domain (RBD) of the S1 subunit interacts with ACE2 during infection, and the S2 subunit is subsequently cleaved by TMPRSS2 protease to trigger virus-host membrane fusion." (PMID 35585971, 2022). "The use of TMPRSS2 pathways leads to more rapid infection as does an intact furin cleavage site within the S protein, as seen in infection with the Alpha and Delta VOC." (PMID 35049999, 2022). "The S1/S2 polybasic cleavage site, which is proteolytically cleaved by the cellular cathepsin L and the transmembrane protease serine 2 (TMPRSS2) protease, is also important for infection." (PMID 36431053, 2022). "Previous work showed that CBD was somewhat better than THC in suppressing the expression of ACE2 and TMPRSS2—two proteins required for infection with SARS-CoV2." (PMID 36144796, 2022). "Although both modes of entry can occur in cell culture, several lines of evidence suggest a preference towards TMPRSS2-dependent fusion during in vivo infection." (PMID 35163273, 2022). "ADAM protease‐targeted inhibitors severely impair lung cell infection by the SARS‐CoV‐2 variants of concern alpha, beta, delta, and omicron and also reduce SARS‐CoV‐2 infection of primary human lung cells in a TMPRSS2 protease‐independent manner." (PMID 35527514, 2022). "To determine if the decrease in TMPRSS2 level by RK-33 had any biological significance on viral entry, we treated Calu-3 cells with RK-33 for 24 h, followed by infection with a SARS-CoV-2 Spike-pseudotyped GFP lentivirus construct." (PMID 36090095, 2022). "Both TMPRSS2 and Furin also have been found to be essential for the efficient infection of SARS-CoV-2." (PMID 35572668, 2022).
infection (continued). "Cardiomyocytes, for example, express significant levels of the ACE2 receptor but lack TMPRSS2, thus, questioning direct cardiomyocyte infection." (PMID 35364700, 2022). "Consistent with prior reports, the viral receptor ACE2 was strongly downregulated after infection, while TMPRSS2 expression was unaffected." (PMID 35587364, 2022). "Co‐expression of ACE2 and TMPRSS2 has been identified as a prerequisite for infection, and expression across different tissues is known to vary between children and adults." (PMID 34735736, 2022). "Infection of TMPRSS2 knockout mice resulted in reduced pathogenicity and replication of monobasic H1N1 or H7N9 and H10-bearing influenza virus strains, as compared to infection of WT mice, thus confirming the TMPRSS2 dependence of these strains." (PMID 35163273, 2022). "The reduced TMPRSS2 expression alters the primary site of infection and the transmission of the virus in the airway, leading to less severe immunopathology." (PMID 35017320, 2022). "We next infected Calu-3 lung cells (known to express endogenous TMPRSS2) with live isolates, and observed significantly greater viral replication for Delta than Omicon, manifesting as early as 24 hours post infection." (PMID 35075452, 2022). "This overlap corresponded with the detection of NP staining, suggesting the necessity of both ACE2 and TMPRSS2 for infection." (PMID 35255100, 2022). "The catalytic activity of TMPRSS2 can be blocked by the trypsin-like serine protease inhibitor camostat, which impairs infection by SARS-CoV-2." (PMID 35631327, 2022). "The infection of SARS-CoV-2 begins with SARS-CoV-2 cleaving its S protein through transmembrane protease serine 2 (TMPRSS-2) and attaching to the ACE-2 receptor." (PMID 35401579, 2022). "SARS-CoV-2 presence upregulated TMPRSS2 expression in syncytiotrophoblast and cytotrophoblast cells, thereby rendering them amenable to infection." (PMID 36177036, 2022). "Orchestration of receptor binding and proteolytic cleavage of SARS-CoV-2 is essential for successful entry and infection; therefore, expression of ACE2 and TMPRSS2 is likely to dictate cell susceptibility and tropism." (PMID 35532162, 2022). "S protein remains inactive in its native state and during infection, it gets activated with the help of proteases of the host cell membrane using a transmembrane protease serine 2 (TMPRSS2) as a primer." (PMID 35747328, 2022). "This is consistent with published evidence that has demonstrated that all these cell types express viral entry factors (ACE2, TMPRSS2) necessary for infection." (PMID 36585637, 2022). "While E64d and camostat effects are dependent on the absence or presence of TMPRSS2, respectively, imatinib was active in both cases, indicating that imatinib effectively inhibits both routes of infection; receptor-mediated-endocytosis and membrane fusion." (PMID 35388061, 2022). "This was supported by increased ACE2/TMPRSS2 expression and subsequently enhanced infection of normal human bronchial epithelial cells (NHBE) and Vero E6 cells with SARS-CoV-2 once pre-treated with dexamethasone." (PMID 36405732, 2022). "The results showed that the viral RNA level in diltiazem-treated cells was significantly lower than that in DMSO-treated cells at 6 h post-infection, indicating that diltiazem affects TMPRSS2-dependent membrane fusion during SARS-CoV-2 infection." (PMID 35176124, 2022). "Another route of infection is via transmembrane protease serine 2 (TMPRSS2) driven cleavage of SARS-CoV-2 escorted through ACE2." (PMID 35852992, 2022). "Having confirmed endogenous expression of ACE2 and TMPRSS2 in both bronchiolar and alveolar organoids, we aimed to evaluate infection of the organoids by a clinical SARS-CoV-2 isolate, Washington strain." (PMID 35360113, 2022). "Our data showed that TMPRSS2-mediated infection is essential for the replication and pathogenicity of SARS-CoV-2 in murine airways and that the Omicron VOC is not an exception in using TMPRSS2 in vivo." (PMID 36243815, 2022).